MIR4292 (microRNA 4292)
Synonyms: hsa-mir-4292
Gene: MicroRNA gene on chromosome 9 (136,830,957 to 136,831,023, forward strand). Ensembl gene ENSG00000265806.
Homologues: Orthologues: chimpanzee MIR4292 (100% identical).